SPP1 (secreted phosphoprotein 1)
Diseases named in the same sentence as SPP1 in open-access papers (continued):
Sharing a sentence is not in itself a finding about the gene and the disease.
tumor (continued). "To elucidate the spatial relationship between SPP1+ macrophages and proliferating tumor cells (MKI67+), we screened for SPP1+ macrophage‐enriched spots on the ST slide, then calculated the surrounding signals of proliferative tumor cells, and finally determined the correlation between the two." (PMID 39716897, 2024). "Similarly, CTHRC1+GREM1+ myCAF communicated with SPP1+ macrophages and tumor cells through integrin signaling, where collagen/integrin pairs and FN1/integrin pairs were prevalent." (PMID 39075108, 2024). "Additionally, in metastatic tumors, MRC1 + CCL18 + macrophages, SPP1 + macrophages, and neutrophils were found to have significantly enhanced expression, suggesting a correlation between macrophage phenotype and tumor stage." (PMID 39068459, 2024). "The population of SPP1 + Macs was dramatically increased in tumor tissue-derived myeloid cells." (PMID 39726047, 2024). "The formation of a tumor immune barrier, containing CAF and secreted phosphoprotein 1 (SPP1)+ macrophages, at the tumor border of HCC patients correlates with reduced response to anti-PD-1 therapy271and, therefore, stroma-modifying therapy is an interesting approach for combination therapy." (PMID 38806159, 2024). "Furthermore, among 10 macrophage and 11 T lymphocyte clusters, CD4-FOXP3 and Mø-SPP1 showed the highest preference in the tumor samples of GBC-LI." (PMID 38822440, 2024). "Thereby, our study identified EGCs as an additional important regulator of SPP1+ TAM differentiation that, together with other cancer-associated stromal cells, may contribute to tumor progression." (PMID 39030280, 2024). "Furthermore, when UPP1-overexpressing tumor cells were co-cultured with macrophages, there was an evident upregulation of SPP1 expression in the macrophages." (PMID 38331898, 2024). "Interestingly, both MNDA+ macrophages and IGKC+ macrophages were enriched in adjacent normal samples, whereas SPP1+ Macs were increased in almost all tumor samples." (PMID 39726047, 2024). "Likewise, computational network analysis of mouse scRNA-seq data suggests Spp1/Cd44 as one pair of top predicted genes of ligand-receptor interaction in tumor ECs-2 and Mφs, respectively." (PMID 38416830, 2024). "Secreted phosphoprotein 1 (SPP1) acts as a tumor cell growth promoter in HCC, targeted by miR‐181c." (PMID 39540710, 2024). "Tumor-infiltrating macrophages were predominantly of the M2 type, with high expression of SPP1." (PMID 39697346, 2024). "SPP1 plays important roles in regulating tumor growth, EMT, metastasis and angiogenesis." (PMID 38956502, 2024). "Knocking down Spp1 significantly decreased tumor sizes with RIL-175." (PMID 39372792, 2024). "In addition, SPP1 + Mac-derived TNF-α and IL-1β promoted the expression of OPN in both tumor cells and macrophages." (PMID 39726047, 2024). "Furthermore, a single-cell transcriptomic analysis involving 14 pairs of iCCA tumors and non-tumor liver tissues classified iCCA into two subtypes according to the expression of S100P and SPP1." (PMID 38339060, 2024). "In addition to the interaction between POSTN+ fibroblasts and SPP1+ macrophages, we were interested in how they influence tumor cells because we found that their interaction weight with tumor cells increased from the NT to A stage." (PMID 38519500, 2024). "For example, an enhanced expression of secreted phosphoprotein 1 (SPP1) could promote DNA damage repair and tumor cell survival in ESCA, thereby leading to resistance to radiotherapy." (PMID 39196978, 2024). "Similarly to ECM-myCAF, IFNαβ-myCAF and TGFβ-myCAF clusters, TREM2+ TAM and SPP1+ TAM cells were detected within the tumor bed." (PMID 38561380, 2024). "Furthermore, the SPP1 and TENASCIN pathways, associated with tumor immune escape and tumor progression, were also enriched in the HAS group." (PMID 39267750, 2024). "Previous studies indicated that SPP1 was an important factor in tumor microenvironment formation." (PMID 38987572, 2024).
tumor (continued). "In this study, we demonstrated that tumor-derived SPP1 could increase lung neutrophil infiltration to form the PMN and subsequently stimulate the formation of NETs to promote HCC lung metastasis." (PMID 39529085, 2024). "Moreover, stimulation with mouse-derived recombinant SPP1 protein induced the expression of pro-tumor genes (such as Arg1, Slc2a1, and Nos2) in MDSCs while repressing the expression of anti-tumor genes (such as Il1b, Tnfa, and Il12b)." (PMID 39066845, 2024). "They discovered that the hypoxic microenvironment promoted SPP1 expression, and SPP1+ macrophages interacted with CAFs to stimulate extracellular matrix remodeling and promoted tumor immune barrier (TIB) structure formation, thereby limiting immune infiltration into the tumor core." (PMID 37612741, 2023). "ROC curve analysis suggested that tissue SPP1 counts could serve as a potential prognostic biomarker for tumor recurrence or progression, with an area under the curve (AUC) of 0.645 when a cut-off of >1370 was used." (PMID 38275392, 2023). "Furthermore, in the tumor tissue, the upregulated ligand-receptor pairs mostly existed in the macrophage-macrophage communication including Thbs1-, Spp1-, Lgals9-, and Csf-related pairs, which were highly related to immunity suppression." (PMID 36718369, 2023). "This suggests that SPP1 expression may be involved in processes related to tissue damage or death within the tumor and that SPP1 may play a role in promoting or modulating inflammatory responses within the tumor." (PMID 38275392, 2023). "Tumor cells at the invasion front induce the increase of SPP1+ macrophages by expressing high levels of HLA‐G, and SPP1+ macrophages secrete IL‐1β to recruit additional SPP1+ macrophages, and together they inhibit anti‐tumor immunity by depleting other immune cells." (PMID 37632718, 2023). "SPP1+ macrophages interacted with CAFs to induce extracellular matrix remodeling and the formation of an immune-excluded phenotype, thereby limiting immune infiltration into the tumor core." (PMID 37267125, 2023). "Finally, the co-expression and interaction between SPP1+TAMs and Treg cells in the tumor microenvironment were analyzed by multiplex immunohistochemistry." (PMID 37675100, 2023). "Ifitm6+, Hcar2+, Retnla+, Spp1+, C1qb+, and Fscn1+ macrophages mainly existed in tumor tissues." (PMID 36718369, 2023). "As reported in other studies, OPN/SPP1 could indeed induce the transition of normal fibroblasts into tumor-promoting CAFs." (PMID 36744260, 2023). "In contrast, genes related to tumor metastasis, such as SPP1 and CENPM, were up-regulated in MM." (PMID 37880239, 2023). "We also compared TCGA tumor samples to GTEx normal samples to determine whether SPP1 and CSF1 were up- or downregulated in HCC." (PMID 37097499, 2023). "The identified MG SPP1-mediated interactions might represent potential targets to modulate MG-lymphocyte crosstalk in the tumor periphery." (PMID 38127790, 2023). "In some tumor-related studies, SPP1 and CSF1 exhibit the same expression trend and function." (PMID 37097499, 2023). "An adenovirus armed with CD40L and 4‐1BBL; activates CD40 and 4‐1BB pathways; Decrease the tumor growth factors (including Spp‐1, Gal‐3, HGF, TGFβ, and collagen type I); Increase cytokines and chemokines, and such DCs potently expanded both antigen‐specific T cells and NK cells." (PMID 36880311, 2023). "Moreover, higher cytoplasmic SPP1 expression was significantly correlated with low-grade tumors and the early tumor stage (Ta)." (PMID 38067407, 2023). "The interaction between SPP1+ macrophages and tumor epithelial cells activated downstream genes to mediate the activation of NF-κB, PI3K/Akt, VEGF, uPA, and MMPs, which could promote endothelial cell proliferation." (PMID 38347955, 2023).
tumor (continued). "Additionally, Nanostring technology allowed to find elevated expression of SPP1 in CD45+ immune compartment compared to CK+ tumor cell compartment as well as strong correlation of SPP1 with macrophage count in CRC tissues." (PMID 36895491, 2023). "Notably, (SPP1)+/− cells synergise with tumour-specific fibroblast activation protein (FAP)+ fibroblasts to establish a desmoplastic reaction, which limits the infiltration of cytotoxic T cells, thus restricting efficacy of checkpoint inhibitor therapy." (PMID 36161514, 2023). "However, only a portion of patient 1’s tumor are SPP1+, which requires further classification and analysis with more patients." (PMID 38239853, 2023). "SPP1+ macrophages from tumor tissues showed high expression of MMP9, MMP12, MMP14, and MMP19, which could contribute to the degradation of the basement membrane for the invasion of tumor cells." (PMID 38347955, 2023). "However, in contrast to other reports that showed OPN/SPP1 was highly expressed in tumor cells, our data indicated that OPN/SPP1 was mainly expressed in macrophages." (PMID 36744260, 2023). "In normal tissues, the proportions of SPP1+ macrophages and p21+ tumor cells were low." (PMID 37090726, 2023). "A study suggests that SPP1 is a predictor of adverse prognosis in HCC patients and that targeting SPP1 might be a potential approach to modulate the tumor microenvironment and enhance response to immunotherapy in HCC." (PMID 36650832, 2023). "However, significant correlations were observed between the cytoplasmic level of SPP1 and the tumor grade (p = 0.046), stage (p = 0.018) and lymph node (p = 0.047)." (PMID 38067407, 2023). "Indeed, when the expression of OPN was investigated in tumor tissues, the OPN gene SPP1 was in the top 5% of overexpressed genes by microarray." (PMID 37444590, 2023). "The enrichment of Macro-SPP1 or Fib-APSN cells at the tumor boundary may be a common characteristic in ICB-insensitive cancers, that deserve further investigations." (PMID 36806082, 2023). "SPP1 is closely related to tumor progress, such as proliferation, migration, and invasion." (PMID 37656377, 2023). "SPP1 is a multifunctional glycoprotein expressed in the macrophages across different tissues and is involved in biological processes such as inflammation, immune response, macrophage migration, tumor proliferation, and invasion." (PMID 37239939, 2023). "The localization of the tumor-promoting immune cells might be supported with the interaction of SPP1 and CD44 in the tumorous ECM." (PMID 37945567, 2023). "In addition, ANGPTL2 and SPP1 mainly distributed in the tumor microenvironment (TME) of CRC tissues." (PMID 37691929, 2023). "In SPP1+ macrophages, the main metabolic pathway was glycolysis, which could promote tumor metastasis via angiogenesis and matrix remodeling." (PMID 38347955, 2023). "Using the Robust Cell Type Decomposition (RCTD) algorithm, we projected cell types based on gene expression matrices from scRNA‐seq data to the spatial transcriptomic map and found that POSTN+ CAFs and SPP1+ macrophages were enriched in another two tumours (P19 and P47, both stage III)." (PMID 38115703, 2023). "Single-cell dataset revealed an enrichment of multiple efferocytosis-related genes in distinct myeloid subsets within the tumor, specifically, SPP1+, ISG15+, C1QC+ macrophages, and CD14+ monocytes in the tumors, which were distinct from the scRNA-Seq from the peripheral blood." (PMID 36439171, 2022). "C4 TAMs (964 cells in residual tumor) express SPP1, TREM2 and APOE." (PMID 35784460, 2022). "One of the mechanisms of SPP1 in tumor promotion was to inhibit T cell activation, which can be used as an immune checkpoint and may compensate for the role of PD-L1 in inhibiting the function of cytotoxic T lymphocytes in CRC." (PMID 35252182, 2022). "Specifically, we identified two ligand–receptor pairs, i.e., LGALS9-SLC1A5 and SPP1-PTGER4 that may represent a fingerprint of functional interactions between tumor cells and TAMs." (PMID 36476645, 2022).
tumor (continued). "Recently, SPP1 has been reported to be involved in the tumor progression of multiple human cancers; however, the role of SPP1 in GC heterogeneity and whether it is associated with the invasiveness and mortality of GC remain unclear." (PMID 36612160, 2022). "The present pan-cancer analyses revealed that SPP1 and its correlated genes might perform their efficacy by regulating tumor immune infiltration in various malignant tumors including HNSCC." (PMID 35875097, 2022). "In summary, our findings suggested that SPP1 could regulate tumorigenesis, tumor progression, and prognosis." (PMID 35067176, 2022). "In addition, they noted that PMEL and SPP1 were overexpressed in the tumor cell cluster whereas lymphoid tissue regions far away from and near, the tumor cell areas were characterized by expression of the immune-related genes CD74 and IGLL5, respectively." (PMID 35590346, 2022). "Furthermore, SPP1 also binds to CD44, causing cell signaling that mediates tumor progression and metastasis." (PMID 36424413, 2022). "In conclusion, this study indicated that SPP1 involved in tumorigenesis, tumor progression, and regulated tumor immune microenvironment, revealing SPP1 might be a potential target for evaluating prognosis and immunotherapy in multiple cancers." (PMID 35067176, 2022). "Furthermore, the expression level of SPP1 was related to the abundance of tumor-infiltrating Tregs and macrophages." (PMID 36292645, 2022). "Although the production of SPP1 by tumor-associated macrophages (TAMs) has been attracting much attention recently, there have been no studies distinguishing the SPP1 expression of cancer cells and TAMs." (PMID 36139536, 2022). "Furthermore, we found that tumor-specific SPP1+ macrophages were a crucial component of intratumor heterogeneity, and that SPP1/CD44-mediated crosstalk played an important role in GC progression." (PMID 36612160, 2022). "Cell—cell communication analysis revealed that SPP1/CD44 interactions between SPP1+ macrophages and their localized tumor epithelial cells could activate downstream target genes in epithelial cells to promote dynamic changes in intratumor heterogeneity." (PMID 36612160, 2022). "There also is a study showing that SPP1 may contribute to tumor progression by promoting immune cell infiltration." (PMID 35027925, 2022). "Taken together, these results demonstrated that SPP1 was up-regulated in multiple cancers suggested that SPP1 may play a crucial biological role in tumor progression." (PMID 36585688, 2022). "Moreover, the expression of Spp1, which is considered a pro-tumor macrophage marker, was higher in uIRI-Can samples than in Sham-Can samples, and it was contained in DEGs of uIRI-Can samples." (PMID 36470862, 2022). "Additionally, these observations revealed that the tumor-specific SPP1+ macrophages that are unique to cancer were an important component of intratumor heterogeneity." (PMID 36612160, 2022). "The high metabolic activity of Ki67+ C1q+ TAMs may be related to the characteristics of active proliferation, while the elevated glycolysis activity of SPP1+ TAMs is also consistent with the hypoxic tumor microenvironment." (PMID 36172359, 2022). "Then, we compared the ssGSEA scores between the SPP1-High group and the SPP1-Low group in TCGA, which demonstrated that SPP1 might participate in the process of macrophage activation, tumor progression, and metastasis." (PMID 36612160, 2022). "Notably, SPP1 can be considered as a marker gene of macrophages with angiogenesis function across eight tumor types, including BRCA, pancreatic adenocarcinoma, lung cancer, CRC, uterine corpus endometrial carcinoma, NPC, OV, and THCA." (PMID 35504878, 2022). "In addition, a significant decrease in SPP1 mRNA level was found in EEF2K knockdown tumour xenografts." (PMID 35184394, 2022).
tumor (continued). "The biological functions of SPP1 are variable, specifically in some certain physiological and pathological conditions, including drug resistance, cell proliferation, invasion, survival, stem-like behavior and tumor metastasis." (PMID 35067176, 2022). "Further in vivo validation using a mouse ESCA xenograft model showed that SPP1 overexpression significantly increased tumor volume while either SPP1 knockdown or pharmacological inhibition of the JAK2‐STAT3 pathway reduced tumor volume in a synergistic manner with radiotherapy." (PMID 35593388, 2022). "SPP1 is involved in tumor immunosuppression and affects the TME." (PMID 36110938, 2022). "SPP1 expression correlated positively with the tumor immune and stromal scores at P < 0.001." (PMID 35067176, 2022). "Our studies indicated that increased anti-SPP1 autoantibody may be more likely to develop ESCC for people with family tumor history." (PMID 36038839, 2022). "We used siRNA to knockdown SPP1 expression in tumor cell lines." (PMID 35067176, 2022). "The immunohistochemical map of a marker of SPP1+ TAMs was also highly expressed in tumor tissues." (PMID 35634956, 2022). "The results showed that si-SPP1 also decreased cell proliferation of these tumor cell lines." (PMID 35067176, 2022). "The volcano plot shows that SPP1 was highly expressed in tumor‐infiltration macrophages." (PMID 35634956, 2022). "Finally, SPP1 significantly elevated cell proliferation and migration in A549, Huh7, HT-29, A2780 tumor cell lines." (PMID 35067176, 2022). "SPP1 is expressed not only by tumor cells but also by stromal cells, such as macrophages." (PMID 36139536, 2022). "But we found thatCRABP2 and SPP1 expressions increase as the malignant tumor property increases." (PMID 35578123, 2022). "The roles of SPP1 in mediating tumor progression also need to be revealed in the future." (PMID 36292645, 2022). "Furthermore, the secreted phosphoprotein 1 (SPP1) gene was identified as a potential driver of tumor evolution." (PMID 40636144, 2022). "Taken together, these findings indicated that SPP1 expression significantly correlated with immune microenvironment and may promote tumor immune tolerance process." (PMID 36585688, 2022). "SPP1 was a promising biomarker for tumor diagnosis and prognosis." (PMID 36292645, 2022). "More recently, SPP1 has been reported to be involved in tumorigenesis by regulating EMT, and this may be a new mechanism of SPP1 mediated tumor invasion and metastasis." (PMID 36266702, 2022). "We also reported the tumor‐promoting effect of SPP1 in ESCA systematically and comprehensively." (PMID 35593388, 2022). "In the present study, we found that SPP1+ TAMs may be involved in tumor angiogenesis by interacting with adjacent CAFEndMT, which is regarded as the initial step of angiogenesis." (PMID 36333338, 2022). "Therefore, it is necessary to pay more attention to the role of SPP1 in different aspects of tumor biology." (PMID 35067176, 2022). "The SPP1 expression is positively correlated with the ESCA tumor stage." (PMID 35593388, 2022). "All these results suggested that downregulation of SPP1 could increase tumor cell death ratio and enhance radiation sensitivity in ESCA." (PMID 35593388, 2022). "However, these analyses also revealed that the enhanced tumor initiation triggered by TIA1 downregulation was associated with an increased expression of ONCs previously identified in HepG2 cells (e.g., Spp1, Ccn2), following TIA1 silencing." (PMID 35406476, 2022). "Furthermore, RNA velocity predicted that tumor-specific SPP1+ macrophages probably originated from THBS1+ macrophages." (PMID 35365629, 2022). "SPP1 which was reported mainly expressed in malignant cells could act as a driver of tumor evolution." (PMID 35634447, 2022). "Furthermore, through simultaneous single-cell and spatial analysis, we demonstrated that SPP1+ macrophages are tumor-specific macrophages unique to cancer and enriched in the deep layer of GC tissue." (PMID 36612160, 2022).